Y_RNA (Y RNA )
Gene: Miscellaneous RNA gene on chromosome 10 (36,626,015 to 36,626,138, reverse strand). Ensembl gene ENSG00000207271.
Homologues: Orthologues: rat Y_RNA (71% identical). Paralogues in human: Y_RNA (71% identical), Y_RNA (70% identical), RNY1P5 (69% identical), Y_RNA (69% identical), RNY1 (68% identical), Y_RNA (68% identical), Y_RNA (67% identical), RNY1P2 (66% identical), Y_RNA (66% identical), RNY1P1 (65% identical), Y_RNA (65% identical), RNY1P11 (65% identical), and 86 more.